AREG (amphiregulin)
Diseases named in the same sentence as AREG in open-access papers (continued):
Sharing a sentence is not in itself a finding about the gene and the disease.
cancer (continued). "AREG, an epidermal growth factor (EGF) receptor ligand, is implicated in multiple cancer types and potently enhances malignant development in both primary and metastatic lesions (Xu, Chiao, & Sun, 2016)." (PMID 31493351, 2019). "AREG has been investigated extensively for its role in oncogenic processes since it was shown to contribute to many of the “hallmarks of cancer” such as metastasis and angiogenesis." (PMID 32082070, 2019). "To further confirm the contribution of AREG to cancer cell phenotypic alterations by specifically eliminating AREG protein itself, we generated a monoclonal antibody (AREG mAb) with high competency in recognizing free AREG in culture conditions." (PMID 31493351, 2019). "Both Trop2+ and AREG+ group coexpression level was the highest (41.42%) than T+A‐(24.62%), T‐A+(21.39%) and T‐A‐(12.56%) groups in cancer tissues and the T+A+ expression level in cancer tissues were higher than that in the matched adjacent tissue." (PMID 28256068, 2017). "Its levels in plasma of NSCLC patients correlate with poor prognosis and AREG was recently found as a signaling molecule in exosomes derived from cancer cell lines." (PMID 28600504, 2017). "EGFR binds Amphiregulin (AREG) that is overexpressed in several cancers such as colon, breast and lung." (PMID 28600504, 2017). "In this study, we showed that AREG expression at both the mRNA and protein levels was higher in GC patients when compared with non-cancer patients and normal tissues." (PMID 27713123, 2016). "Clinically, AREG is overexpressed in different types of cancers, such as breast, lung and colon cancers." (PMID 27589805, 2016). "EGFR ligands implicated in human cancers, include EGF, EREG, amphiregulin (AREG), heparin-bound EGF (HB-EGF) and transforming growth factor alpha (TGFα)." (PMID 26958807, 2016). "We found that both mRNA and protein expression of AREG were increased in the tissues of GC patients when compared to tissues from non-cancer patients or normal tissues." (PMID 27713123, 2016). "Several substrates of ADAM15, including EGFR ligands such as HB-EGF, TGFα, amphiregulin, betacellulin, and other factors including Notch, and cytokines have been identified in cancer cells." (PMID 26930657, 2016). "AREG plays a central role in numerous physiological and pathological processes, especially in cancer progression and development." (PMID 27765922, 2016). "The role of AREG in cancer development and progression is supported by clinical data showing that AREG can serve as a prognostic and/or a predictive biomarker." (PMID 27391842, 2016). "Other functional aspects for AGR2 reported in the literature include regulation of amphiregulin expression, promotion of cell adhesion, cancer spread via regulation of cathepsins, and cancer cell survival." (PMID 27283903, 2016). "Analysis by IHC also revealed that increasing levels of AREG protein correlated with the stage of cancer development and progress." (PMID 27713123, 2016). "Amphiregulin (AREG) is a member of the EGF family that contributes to cancer proliferation and progression." (PMID 25644309, 2015). "AGR2 expression in cancer cells induces the expression of amphiregulin (AREG) and in intestinal IEC-6 cells the transcription factor CDX2." (PMID 25111734, 2014). "Whereas the role of E acting through AREG in mammary gland development andbreast cancer has been emphasized, the current studies implicate P as another potential mediator of AREGaction." (PMID 23705924, 2013). "AREG has been reported to be overexpressed in aggressive forms of cancer, and distinct signaling properties have been reported for EGFR and AREG with respect to endocytosis of ligand-receptor complexes, and initiation of downstream signaling." (PMID 23762360, 2013). "We first focused on PR-dependent transcriptional regulation of the paracrine growth factor gene amphiregulin (AREG) playing important role in cancer." (PMID 23029355, 2012).
cancer (continued). "Limited studies, to date, have demonstrated that exosomes expressing amphiregulin and HSP90α can increase cancer cell motility and migration." (PMID 23251413, 2012). "Amphiregulin is a well-studied growth factor with functions in various cell processes and is upregulated in different forms cancer and proliferative diseases." (PMID 21298020, 2011). "All these genes (AREG, GREB1, TFF1 and TFF3) were up-regulated in ER+ carcinomas compared to ER- carcinomas (AREG was only borderline significant)." (PMID 21812955, 2011). "Importantly, the fibrotic TME creates a physical barrier that impedes drug delivery and contributes to drug resistance, further highlighting the importance of targeting AREG in cancer treatment." (PMID 40725192, 2025). "By disrupting the AREG-mediated crosstalk between cancer cells and stromal components, these approaches may overcome the limitations of conventional cancer therapies and provide new avenues for clinical intervention." (PMID 40725192, 2025). "Furthermore, we analyze the interplay between fibrosis and cancer, examining how AREG contributes to cancer progression within fibrotic microenvironments and its potential role in chemoresistance." (PMID 40725192, 2025). "The relevance of AREG inhibition is further highlighted by the observed changes in the expression of the ErbB receptor family (ErbB1-ErbB4), which comprises a network of receptor tyrosine kinases fundamental to epithelial carcinoma biology." (PMID 41515404, 2025). "Additionally, we review recent advances towards therapeutic targeting of EREG and AREG in cancer through the development and use of EREG- and AREG-targeted monoclonal antibodies (mAbs) as well as antibody-drug conjugates (ADCs)." (PMID 40727266, 2024). "AREG was localized in the endoplasmic reticulum, extracellular region, and nucleus and was expressed at slightly greater levels in adjacent tissues than in cancer tissues (P < 0.05)." (PMID 38532419, 2024). "Thus, more extensive investigation and precise elucidation of the molecular mechanism of AREG overexpression in cancer cells, including CRCs, are needed to support its future clinical application." (PMID 39452130, 2024). "In cancer, extensive research on Amphiregulin has emerged since the 2010s." (PMID 39199549, 2024). "This also suggests that AREG might be upregulated in different cell types, such as immune and vascular cells, within the cancer microenvironment to promote cancer growth." (PMID 39452130, 2024). "Consistent with previous experiments using HCT116 Rab11a‐exosome preparations and HCT116 target cells and with other cancer sEVs, this effect was blocked by a neutralising anti‐AREG antibody, which suppressed the sEV‐induced activation via phosphorylation of the downstream signalling target ERK." (PMID 38887984, 2024). "Our findings suggest that increased AREG expression in CRC cells might be a mechanism of drug resistance to 5-FU in a Visfatin-containing cancer microenvironment and under obese conditions." (PMID 39452130, 2024). "Finally, we will conclude with recent progress made towards therapeutically targeting EREG and AREG in cancer with novel mAbs and ADCs." (PMID 40727266, 2024). "In previous reports, Akt activation was found to increase the activity of A Disintegrin and Metalloproteinase 17 (ADAM17), which increases the shedding of heparin-binding EGF (HB-EGF) and amphiregulin (AREG) from the cancer cell surface, leading to EGFR activation." (PMID 37779142, 2023). "Studies have also demonstrated that AREG could participate in the cancer progression mediated by EGFR50,51." (PMID 37907576, 2023). "Several previous reports have documented the role of CCL5 and AREG in cancer progression." (PMID 37553567, 2023). "Accordingly, cancer drugs targeting amphiregulin RNA expression are being developed." (PMID 36982582, 2023).
cancer (continued). "Moreover, the ligand-receptor pair consisting of EGFR ligand and COPA or AREG was also the key ligand-receptor pair in the communication between myofibroblasts and cancer stem cells." (PMID 35620271, 2022). "Other studies reported the role of Amphiregulin in cancer cell proliferation." (PMID 35732465, 2022). "Cancer cells of BC‐LM and LC‐LM also disrupt the blood–CSF barrier by deriving C3 to activate the C3a receptor in the choroid plexus epithelium to allow plasma amphiregulin and other mitogens entering the CSF, which also promotes cancer cells growth in CSF." (PMID 35678121, 2022). "For that, we inhibited the expression of HB-EGF or AREG in the 4T1 and E0771 cells using 2 siRNAs, cocultured these cells with BMDMs, and evaluated the macrophage-induced invasion of WT cancer cells, using the Boyden chamber assay." (PMID 35998057, 2022). "It is known that ERBB2 and AREG stimulate glucose uptake and could regulate mitochondrial functions through switching cancer cell metabolism from OXPHOS to glycolysis to enhance cell growth." (PMID 35328408, 2022). "Furthermore, the GEPIA online correlation database (gepia.cancer-pku.cn) revealed a positive association between WBP2 and YAP target genes, including CTGF, CYR61, and AREG." (PMID 33837178, 2021). "Moreover, functional studies indicate that AREG can perform as a pro‐oncogenic factor, affecting most cancer hallmarks." (PMID 34382262, 2021). "And GSEA revealed AREG, CAV1 and STAG3 were associated with dysregulated pathways in cancer." (PMID 33712015, 2021). "Notably, EGFR and its receptors, including TGFB1, MIF, HBEGF, GRN, COPA, and AREG, were upregulated in cancer cells and fibroblasts." (PMID 34326696, 2021). "Thus, Amphiregulin participates in cancer cell proliferation, migration, invasion, and angiogenesis in human carcinomas, so Amphiregulin was incriminated as a predictive biomarker of anti-EGFR therapy for most EGFR-driven carcinomas." (PMID 33906293, 2021). "The MEPT-induced changes in amphiregulin and PR isoform expression may contribute to its cancer protective capabilities." (PMID 31355130, 2019). "The competency of AREG mAb‐caused reversion of chemotherapy‐elicited changes in cancer cells was further supported by similar changes in several EMT‐specific markers, data consistent with our findings from cancer cell‐based in vitro assays." (PMID 31493351, 2019). "Besides genes expressed in common with hESCs, cancer cells expressed Epiregulin (EREG) and Amphiregulin (AREG) of the EGF-receptor (EGFR) pathway, generally associated with progressed cancer." (PMID 31758153, 2019). "Through in vitro assays, we revealed that AREG is one of the major effectors of the full SASP spectrum, as elimination of AREG from stromal cells caused substantially weakened cancer cell malignancies, including proliferation, migration, invasion, and more importantly chemoresistance." (PMID 31493351, 2019). "However, the malignancy‐promoting effects of AREG on cancer behaviors were almost completely abrogated upon AREG depletion from PSC27." (PMID 31493351, 2019). "Together, our data consistently suggested that either controlling EGFR as a plasma membrane receptor on recipient cells or targeting AREG as a soluble factor from damaged stromal cells can significantly deprive cancer cells of acquired resistance to chemotherapeutic agents." (PMID 31493351, 2019). "More recent studies from the cancer field provide direct evidence for a functional role of HIF2-alpha in the induction of AREG expression during conditions of hypoxia via direct binding of HIF2-alpha to the AREG promoter, and thereby increasing its transcriptional activity." (PMID 29483579, 2018). "The prognostic relevance of IGF1R and AREG was assessed using a multivariate proportional hazards model adjusted for the following established clinical prognostic factors: treatment arm, gender, age, cancer stage, and histological type." (PMID 26884344, 2017).
cancer (continued). "However, in our analysis, we only identified 1 gene, AREG, from the ion-channel family to be predictive of histologic grades of cancer." (PMID 28122498, 2017). "Furthermore, amphiregulin is involved in cancer progression and has become the focus of several basic, translational, and clinical investigations." (PMID 29225597, 2017). "EGF stimulated AREG production was tightly regulated in normal and transformed cell lines, suggesting that failure to control EGFR induced AREG expression may be a crucial step in carcinogenesis and cancer progression." (PMID 27669890, 2016). "Previous studies found that over-expression of AREG could serve as a cancer biomarker in a various cancer types, but its role in GC progress was still undefined." (PMID 27713123, 2016). "As a pro-oncogenic molecule, aberrant expression of AREG could promote abnormal activation of cell signaling transduction and subsequent gene transcription, which, in turn, could lead to cancer development and progression." (PMID 27713123, 2016). "Functional studies using cancer cell lines have shown that AREG is involved in several hallmarks of cancer, such as inhibiting apoptosis, promoting cancer cell invasion and metastasis, enhancing angiogenesis and endowing cancer cells with unlimited replicative potential." (PMID 27589805, 2016). "Taken together, the literature suggests that AREG-activated aberrant signaling pathways could be a target for cancer therapy." (PMID 27713123, 2016). "Functional studies show that AREG is involved in most of the hallmarks of cancer." (PMID 27391842, 2016). "Indeed, studies have reported that AREG stimulates directional migration and invasion of human cancer cells." (PMID 26503469, 2015). "Moreover, we observed that overexpression of AREG shRNA inhibited cancer migratory ability by approximately 60%." (PMID 26503469, 2015). "AREG has been shown to increase cell migration and metastasis in various human cancer cells." (PMID 26503469, 2015). "In addition to TGF-α, amphiregulin (AREG) is another EGFR ligand that is known to promote cancer growth and progression." (PMID 26503469, 2015). "The inverse correlation between SOCS6 and AREG mRNA levels in human cancers was intriguing." (PMID 25180228, 2014). "We therefore asked whether simultaneously silencing fibroblast-secreted amphiregulin and cancer cell expressed CCR1 was more efficacious than blocking either alone." (PMID 24068959, 2013). "We recently reported the distribution of serum Amphiregulin in 85 cancer-free women." (PMID 24010672, 2013). "Given the involvement of AREG in cancer development/metastasis as a paracrine growth stimulus, aggressive phenotype of PRA rich tumors might at least in part be attributed to elevated AREG levels which may enhance the proliferation of nearby PR negative cells." (PMID 23029355, 2012). "Therefore, suppressing AREG activity may be critical for mitigating fibrosis in EGFR inhibitor-treated cancer patients, as indicated by studies in multiple tissue contexts." (PMID 40725192, 2025). "Interestingly, AREG stimulates the activation of the epithelial–mesenchymal transition (EMT) programme, downregulating epithelial cell marker expression and increasing the expression of mesenchymal markers; in this way, AREG drives the development of fibrotic disease and cancer invasion." (PMID 40868999, 2025). "Therefore, we suggest that targeting AREG or the AREG-dependent signaling pathway could contribute to minimizing drug resistance and cancer cell proliferation." (PMID 40422206, 2025). "However, clinical application of the EGFR-neutralizing drug cetuximab has shown that AREG expression/secretion levels can compensatorily increase in the patient’s cancer microenvironment, leading to drug resistance development and being a predictive marker for anti-EGFR treatment." (PMID 39452130, 2024).
cancer (continued). "Notably, although anti-AREG therapy has been considered a possible therapeutic strategy in cancer treatment, the competing concept indicates that EGFR-targeting therapy might still be the predominant developing direction." (PMID 39452130, 2024). "Similarly, the role of AREG in chemoresistance has been described in other cancer subtypes." (PMID 38831884, 2024). "This could help block the activity of EGFR ligands implicated in cancer and inflammation (e.g., AREG, EREG,) without affecting the function of TGFα in protection of the skin and intestinal barrier." (PMID 36361585, 2022). "Yet, we show that the secretion of both HB-EGF and AREG is crucial for the invasion-supporting phenotype of the macrophages, and we were able to rescue the impaired ability of macrophages educated by Adam17–/– cells to induce cancer cell invasion by adding rHB-EGF or rAREG to the cocultures." (PMID 35998057, 2022). "Moreover, GSEA revealed that AREG, ATF3, ZFP36, and DUSP1 may regulate OSA via inflammation and contribute to OSA-related cancer risk." (PMID 35372438, 2022). "Moreover, the AREG/EGFR signaling pathway may be involved in cancer progression through enhanced Treg cell function, leading to the activation of NFκB, which is closely related to neoadjuvant chemotherapy response and survival of patients with EAC." (PMID 34724890, 2021). "Moreover, HB-EGF and amphiregulin as EGFR ligands are highly elevated in various types of cancer cells, including CC cells, and significantly enhances the survival of cancer cells by activation of EGFR and the extracellular-signal-regulated kinase (ERK) pathway." (PMID 32708604, 2020). "Therefore interfering with the regulation of Foxp3 by AREG in cancer patients could lead to Foxp3 protein degradation in Treg cells and provide a potential novel therapeutic target for cancer treatment." (PMID 29102676, 2018). "However, this seemingly has no bearing on the cancer-promoting effect of ferric citrate, considering the results of prior murine studies and, collectively, we conclude that amphiregulin regulation by chelated iron is unrelated to increased speed of cancer cell proliferation." (PMID 29682205, 2018). "Furthermore, AREG also contributes to therapeutic resistance to several cancer treatments." (PMID 30517191, 2018). "High expression of AREG may also be considered a promising target for cancer chemotherapy." (PMID 27713123, 2016). "Genes including E-cadherin (Cdh1, up), amphiregulin (Areg, down), c-Met/hepatocyte growth factor receptor (Met, down) and c-Myc (Myc, down) were notable examples of genes involved in cell growth, differentiation and cancer that were significantly regulated by Tcf7l2 silencing." (PMID 25414334, 2014). "Importantly, AREG has also been shown to contribute to the neoplastic phenotype of human HCC cells (Castillo 2006 Cancer Research) and therefore the CCL4 model could be used to further study the role of AREG in hepatocarcinogenesis." (PMID 20618941, 2010). "Pathological diagnoses revealed cancer occurrence rates of 16.7%, 100%, 66.7%, 50% and 50% in the wild-type (WT), CES-SV40 untreated, anti-AREG, FK866, and anti-AREG + FK866 groups, respectively." (PMID 40976783, 2025). "AREG, a ligand of the EGFR, plays a crucial role in promoting cancer cell proliferation, survival, angiogenesis, invasion, metastasis, and the development of drug resistance." (PMID 40725192, 2025). "Next, we analyzed the correlation between AREG and ESR1 using the published Cancer Cell Line Encyclopedia (CCLE) database." (PMID 40422206, 2025). "Amphiregulin (AREG), is an epidermal growth factor ligand of EGFR 9, further promoting distant metastasis, anti-apoptosis, and drug resistance in cancer." (PMID 38904011, 2024). "AREG, a ligand for the epidermal growth factor receptor (EGFR), is known to play a critical role in the development and progression of various cancers, as well as in the resistance to radiation and chemotherapy." (PMID 39451251, 2024).